NOC3L (NOC3 like DNA replication regulator)
Description:
May be required for adipogenesis.
Synonyms: AD24; C10orf117; FAD24; FLJ12820
Tractability: Small molecule: a structure with a bound ligand is known. PROTAC: UniProt records ubiquitination sites on it; ubiquitination databases record sites on it; its protein half-life has been measured.
Gene: Protein-coding gene on chromosome 10 (94,333,226 to 94,362,982, reverse strand). Ensembl gene ENSG00000173145.
Subcellular location: Nucleus, nucleolus; Nucleus speckle
Subcellular location (Human Protein Atlas): Nucleoli; Nucleoli rim; Nucleoplasm
Gene Ontology:
Molecular function: RNA binding; chromatin binding
Biological process: DNA replication initiation
Cellular component: nucleolus; nucleoplasm; nuclear speck; nucleus
Genetic constraint (gnomAD): Loss-of-function variants: 48 observed, 56.55 expected, observed/expected ratio (o/e) 0.85, 90% interval 0.67 to 1.08. The upper end of that interval is the gene's LOEUF score, 1.08, which puts it in group 4 of 6, group 1 being the genes least tolerant of losing a copy. Missense variants: 581 observed, 633.81 expected, observed/expected ratio (o/e) 0.92, 90% interval 0.86 to 0.98. Synonymous variants: 214 observed, 222.07 expected, observed/expected ratio (o/e) 0.96, 90% interval 0.86 to 1.08.
Homologues: Orthologues: chimpanzee NOC3L (99% identical), macaque NOC3L (98% identical), pig NOC3L (94% identical), dog NOC3L (94% identical), guinea pig NOC3L (92% identical), rabbit NOC3L (92% identical), mouse Noc3l (90% identical), rat Noc3l (90% identical), tropical clawed frog noc3l (72% identical), zebrafish noc3l (67% identical), Drosophila melanogaster Noc3 (34% identical), Caenorhabditis elegans C37H5.5 (30% identical).
Diseases named in the same sentence as NOC3L in open-access papers:
NOC3L is named in the same sentence as 12 diseases in open-access papers, as found by Europe PMC text mining. Sharing a sentence is not in itself a finding about the gene and the disease. The quoted sentences say what the papers report.
chromophobe renal cell carcinoma (1 paper, 2025). Chromophobe renal cell carcinoma is a rare subtype of renal cell carcinoma, originating from the intercalating cells of the collecting ducts and macroscopically manifesting as a well-circumscribed, highly lobulated, solid tumor that is usually diagnosed at an early stage. "Expression profiling across diverse tumor types revealed distinct patterns for CEBPZ, NOC2L and NOC3L, with them being elevated in several cancers, yet markedly reduced in AML and kidney chromophobe carcinoma (KICH)." (PMID 40827841, 2025). "Among kidney cancer subtypes, chromophobe renal cell carcinomas (KICH) showed consistently and significantly reduced expression levels of CEBPZ, NOC2L and NOC3L, whereas other subtypes, such as KIRC (clear cell) and KIRP (papillary), displayed more variable expression patterns." (PMID 40827841, 2025).
colorectal cancer (1 paper, 2023). A primary or metastatic malignant neoplasm that affects the colon or rectum. "In addition, NOLC1 may be associated with MCM10, HELLS, NOC3L, and other genes through participating in Wnt signaling pathways and jointly regulate the occurrence and development of colorectal cancer under the influence of the tumor microenvironment and many other influencing factors." (PMID 37670166, 2023).
kidney cancer (1 paper, 2025). Primary or metastatic malignant neoplasm involving the kidney. "These distinct patterns suggest a possible dual behavior of the NOC proteins in kidney cancers – whereas CEBPZ and NOC3L might function cooperatively, NOC2L might act independently or even antagonistically in certain contexts." (PMID 40827841, 2025).
ovarian carcinoma (1 paper, 2021). A malignant neoplasm originating from the surface ovarian epithelium. "Further analysis indicated that PUS7 may interact with NOC3L and PUS1 to regulate ovarian cancer proliferation via modulation of DNA replication and the cell cycle." (PMID 34827123, 2021).
tumor (2 papers, 2023 to 2025). "We analyzed the expression across diverse tumor types based on the hypothesis that CEBPZ, NOC2L and NOC3L form regulatory heterodimers that modulate this process." (PMID 40827841, 2025).
NOC3L also shares sentences with these, for which no sentence is quoted: carcinoma (2 papers); adenoma (1); gastric cancer (1); major depressive disorder (1); rectum adenocarcinoma (1); Sepsis (1); stomach adenocarcinoma (1).